METTL3 (methyltransferase 3, N6-adenosine-methyltransferase complex catalytic subunit)
Diseases named in the same sentence as METTL3 in open-access papers (continued):
Sharing a sentence is not in itself a finding about the gene and the disease.
gastric cancer (continued). "Additionally, METTL3 increases the m6A modification of PBX1 mRNA, enhancing its stability, which, in turn, upregulates GCH1 expression and Tetrahydrobiopterin(BH4) levels in gastric cancer cells, promoting tumor growth and metastasis." (PMID 39791162, 2025). "For example, LINC00470 interacts with METTL3 to promote PTEN mRNA degradation, promoting gastric cancer (GC) progression." (PMID 38166703, 2024). "For instance, SP1 regulates lncRNA THAP7-AS1 at transcriptional level to increase its expression, while METTL3 acts as m6A regulator in post-transcriptional level to promote its stability in an IGF2BP1-dependent manner, thereby increasing its function as an oncogenic lncRNA in gastric cancer." (PMID 38075202, 2024). "In addition, IGF2BP3 and METTL3 improve the expression of transcription factor HDGF by directly recognizing and binding the m6A-modified HDGF, which transcriptionally accelerates the expression of GLUT4 and ENO2 to facilitate glycolysis in gastric cancer." (PMID 37280679, 2023). "Moreover, unlike other m6A regulators, METTL3 was widely participated as an oncogene in different aspects of gastric cancer progression, including cell growth, survival and metastasis." (PMID 37344779, 2023). "The role of methyltransferase-like 3 (METTL3), which participates in catalyzing N-methyladenosine (m6A) RNA modification, in gastric cancer (GC) is unclear." (PMID 35574388, 2022). "For example, METTL3 activates dendritic cells and initiates activation of cytotoxic T lymphocytes by increasing m6A levels of CD40, CD80, and TLR4; METTL3 overexpression promotes gastric cancer progression (GC) and liver metastasis through angiogenic and glycolytic pathways." (PMID 35281520, 2022). "Human gastric cancer cells (AGS and MKN-45) were selected as observation objects, and lentiviral-mediated shRNA was used to silence the expression of METTL3 to further explore the effect of METTL3 on the proliferation, migration, and invasion of gastric cancer cells in vitro." (PMID 34394353, 2021). "Mechanically, Mettl3 could activate zinc finger MYM-type containing 1 (ZMYM1) toward genes complex of chromatin via m6A modification, hence promoting epithelial–mesenchymal transition (EMT) and metastasis of gastric cancer." (PMID 33681207, 2021). "For example, the interaction between LINC00470 and METTL3 facilitated the degradation of PTEN mRNA and further contributed to the development and progression of gastric cancer (GC)." (PMID 33879256, 2021). "Interestingly, miR-4429 inhibited the expression of METTL3, resulting in down-regulation of SEC62 expression, thereby preventing the progression of gastric cancer; LncRNA LINC00470 is significantly up-regulated in gastric cancer tissues and cell lines." (PMID 35070987, 2021). "However, the functional and regulating mechanisms of METTL3 in human gastric cancer have not yet been understood." (PMID 30886897, 2019). "However, methylation is not the only mechanism by which METTL3 promotes gastric cancer progression." (PMID 39678510, 2024). "Moreover, a recent study highlighted that HBx might increase the MYC expression level by inducing the methyltransferase-like protein 3 (METTL3)-mediated N6-methyladenosine (m6A) modification of MYC mRNA, which promoted gastric cancer onset and progression in preclinical analysis." (PMID 36936956, 2023). "High expression of METTL3 has been reported to be an oncogene in multiple solid tumors, such as hepatocellular carcinoma (HCC), non-small cell lung cancer (NSCLC), gastric cancer (GC), colorectal cancer (CRC), and bladder cancer (BLC)." (PMID 34745970, 2021). "METTL3-mediated m6A modification was critical for EMT and metastasis of gastric cancer (GC)." (PMID 34345203, 2021).
gastric cancer (continued). "In addition, upregulation of METTL3 in gastric cancer promotes tumor angiogenesis and glycolysis by promoting IGF2BP3-dependent hepatoma-derived growth factor (HDGF) mRNA stability, which is essential for increasing in glycolysis by activating GLUT4 and ENO2 in gastric cancer cells." (PMID 34616742, 2021). "In previous studies, METTL3 was found to have an adverse influence on acute myeloblastic leukaemia (AML), breast cancer (BC), ovarian carcinoma, bladder cancer (BC) and gastric cancer (GC)." (PMID 33059689, 2020). "Similarly, miR-4429, another potential therapeutic target in gastric cancer (GC), targets and downregulates METTL3 to inhibit m6A-induced stabilization of SEC62, which in turn inhibits cell proliferation and induces apoptosis in GC cells." (PMID 32443966, 2020). "However, the function and mechanism of METTL3 in gastric cancer have not been studied yet." (PMID 30886897, 2019). "In our recent research, we found that exosomal Thrombospondin 1 (THBS1) derived from gastric cancer (GC) cells regulates METTL3- or IGF2BP2-mediated m6A modification, activating the RIG-I-like receptor signaling pathway in Vγ9Vδ2 T cells, thereby enhancing their cytotoxicity against GC cells." (PMID 39987091, 2025). "More than that, we tested a significant negative correlation between METTL3 and ANGPTL3 in 62 pairs of gastric cancer tissues." (PMID 37344779, 2023). "METTL3 plays a dual role as either an oncogene or a tumor suppressor gene in various types of cancers, including hepatocellular carcinoma (HCC), hepatoblastoma, gastric cancer (GC), colorectal cancer (CRC), non-small cell lung cancer (NSCLC), and bladder cancer (BLC)." (PMID 35296338, 2022). "Increased METTL3 expression and decreased SOCS2 protein level was also reported to increase cellular proliferation in gastric cancer cells although no STAT activity could be established in this study." (PMID 33814008, 2021).
colorectal cancer (225 papers, 2019 to 2026). A primary or metastatic malignant neoplasm that affects the colon or rectum. "The expression of METTL3 was not only significantly upregulated in colorectal cancer and associated with a poor prognosis in patients but also showed the positive correlation with RanGAP1 across TCGA, KMplot, GSE39582 and GSE161158 datasets." (PMID 38267624, 2024). "This study aimed to reveal the underlying mechanism by which METTL3 in regulates the metastasis of colorectal cancer (CRC)." (PMID 36348020, 2023). "In breast cancer and colorectal cancer, METTL3-mediated m6A methylation has been repeatedly linked to doxorubicin and oxaliplatin resistance." (PMID 36932427, 2023). "And METTL3 restricted YPEL5 expression in an m6A-YTHDF2-dependent manner also became an important cause of colorectal cancer growth and metastasis." (PMID 37344779, 2023). "The role of METTL3-mediated N6-methyladenosine (m6A) modification has been elucidated in several cancers, but the concrete mechanism underlying its function in colorectal cancer is still obscure." (PMID 38001065, 2023). "METTL3 was shown to cause the activation of mTORC1 signaling and colorectal cancer development in an m6A-dependent manner." (PMID 36058934, 2022). "The abnormal m6A mutation in large intestine cancer was shown to be induced by overexpression of METTL3, which has been linked to tumor spread, and METTL3 was downregulated in STAD tissues in this investigation." (PMID 36620557, 2022). "Recent studies have shown that METTL3 is upregulated and associated with poor prognosis in gastrointestinal malignancies, including liver cancer, pancreatic cancer and colorectal cancer." (PMID 35223847, 2022). "In colorectal cancer and melanoma, loss of METTL3 and METTL14 enhanced the sensitivity to anti-PD-1 treatment." (PMID 35806168, 2022). "In colorectal cancers with low mutational burden, which are resistant to immunotherapy, depletion of METTL3 and METTL14 increases the expression of CD8+ T cells and the secretion of IFN-γ via the m6A reader YTHDF2." (PMID 34616742, 2021). "For example, it was revealed that a poor prognosis of colorectal cancers is associated with a high level of m6A RNA, and in these cells, there is an overexpression of METTL3, METTL16, and WTAP regulatory proteins." (PMID 34357041, 2021). "The loss of METTL3 or METTL14 was shown to enhance the sensitivity of colorectal cancer and melanoma to anti-PD-1 treatment." (PMID 34858499, 2021). "The deficiency of METTL3 resulted in a significant decrease in the levels of these three pri-miRNAs and significantly affected the growth and progress of colorectal cancer." (PMID 34484567, 2021). "The overexpression of miR-877 can partially reverse the effect caused by METTL3 gene knockdown, indicating that METTL3-mediated m6A methylation of pri-miRNAs influence the mitochondrial metabolism and cell fate of colorectal cancer cells." (PMID 34484567, 2021). "The overexpression of miR-877 can partially reverse the effect caused by METTL3 gene knockdown, indicating that METTL3-mediated m6A methylation of pri-miRNAs influences the mitochondrial metabolism and cell fate of colorectal cancer cells." (PMID 34484567, 2021). "Specifically, high expression of METTL3 was significantly associated with poor survival in esophageal and colorectal cancers (p<0.05)." (PMID 32863943, 2020). "Analyses of the Cancer Genome Atlas (TCGA) datasets show that the highly expression of METTL3 mRNA in the metastatic colorectal cancer tissue is positively associated with poor prognosis of patients." (PMID 33372610, 2020). "Li et al50 showed that METTL3 expression was higher in colorectal carcinoma metastatic tissues and was associated with a poor prognosis." (PMID 32615646, 2020). "Moreover, upregulated expression of METTL3 in colorectal cancer is associated with an unfavorable prognosis, a more advanced disease stage, and decreased survival rates." (PMID 40986143, 2025).
colorectal cancer (continued). "Furthermore, in colorectal cancer, METTL3 overexpression has been associated with reduced cellular migration and invasion by affecting the p38/ERK pathway." (PMID 38966069, 2024). "However, little researches are focused on the underlying mechanism of METTL3 in the development of colorectal cancer." (PMID 31492150, 2019). "Taken together, METTL3 and its associated pathway are crucial for colorectal carcinogenesis as well as glycolysis pathway, and targeting this pathway may be pivotal in the prevention and treatment of colorectal cancer." (PMID 32245489, 2020). "In the context of colorectal cancer, Mettl3 plays a significant role by inducing the translation of GLUT1 in an m6A-dependent manner." (PMID 41517663, 2026). "Here we show that the m6A RNA methyltransferase METTL3 acts as a key regulator of this suppression in colorectal cancer (CRC)." (PMID 42135281, 2026). "A study exploring lactation and TME showed that lactate accumulation in TME can effectively induce upregulation of methyltransferase-like 3 (METTL3) in TIMs through H3K18 lactation, which is associated with poor prognosis of colorectal cancer." (PMID 41041328, 2025). "For instance, Fusobacterium nucleatum significantly reduces m6A modification in colorectal cancer cells and tissues by down-regulating the m6A methyltransferase METTL3, thereby accelerating colorectal cancer aggressiveness and metastasis." (PMID 40442779, 2025). "METTL3 mediates Ran GTPase activating protein 1 (RanGAP1) to contribute to the progress of colorectal cancer (CRC)." (PMID 41256854, 2025). "Specifically, METTL3-induced m6A methylation of Matrix metallopeptidase 9 (MMP9) mRNA can promote colorectal cancer proliferation." (PMID 40986143, 2025). "METTL3 overexpression facilitates colorectal cancer cell metastatic progression through the miR-1246–SPRED2–MAPK signaling axis." (PMID 40986143, 2025). "By targeting the BHLHE41–CXCL1/CXCR2 signaling axis, METTL3 promotes colorectal cancer progression through remodeling of the inflammatory TME." (PMID 40986143, 2025). "For example, METTL3 can promote the progress of esophageal cancer, colorectal cancer, pancreatic cancer and other cancers, and the mechanisms of promoting the occurrence of different targets among them are also different." (PMID 41256854, 2025). "In colorectal cancer, METTL3 promotes the stability of SOX2 mRNA by catalyzing its m6A modification, thereby promoting tumor development." (PMID 40003919, 2025). "In colorectal cancer, METTL3 expression is elevated in metastatic tumors, and METTL3 drives cell migration, invasion, and metastasis." (PMID 41301491, 2025). "For instance, in a senescence model of colorectal cancer cells, N6-adenosine-methyltransferase 70 kDa subunit (METTL3) was upregulated, leading to N6-methylation of CDKN2B mRNA, which increases its stability, expression and protein levels." (PMID 40634753, 2025). "In colorectal cancer, targeting METTL3 reprograms the TME by lowering pro-tumor chemokines (CXCL1, CXCL5, CCL20) and enhancing antitumor responses, consistent with a METTL3→chemokine axis that favors myeloid recruitment and immune evasion." (PMID 41280938, 2025). "METTL3 facilitates the EMT in colorectal cancer by adding m6A modifications to SNAIL mRNA, which enhances its stability." (PMID 40356596, 2025). "In colorectal cancer, circQSOX1 undergoes METTL3-mediated m6A methylation and exhibits enhanced stability upon IGF2BP2 binding." (PMID 40986143, 2025). "In colorectal cancer, METTL3 has been shown to have an oncogenic role by stabilizing HK2 and SLC1A2 mRNA via the IGF2BPs axis, regulating glycolytic metabolism and cell proliferation." (PMID 40746529, 2025). "METTL3 facilitates pulmonary metastasis of colorectal cancer by targeting the m6A-Snail-CXCL2 axis to recruit M2-type immunosuppressive macrophages." (PMID 38605400, 2024).
colorectal cancer (continued). "METTL3 promotes colorectal cancer progression by regulating the m6 A-CRB3- Hippo axis, and CRC patients with high m6A or METTL3 levels have shorter overall survival." (PMID 39289775, 2024). "Increased expression of METTL3 in colorectal cancer demonstrated dual functionality in gene regulation, encompassing both methyltransferase activity-dependent and -independent functions." (PMID 39136000, 2024). "For example, METTL3 has been found to play a role in the progression of colorectal cancer by targeting the m6A-BHLHE41-CXCL1/CXCR2 axis, resulting in the inhibition of antitumor immunity." (PMID 38649363, 2024). "METTL3 was shown to be involved in the tumorigenesis and metastasis of colorectal cancer trough YPEL5 expression inhibition in a YTHDF2-dependent manner." (PMID 39136000, 2024). "In colorectal cancer, METTL3 influences stem cell frequency and tumor progression by regulating SOX2 mRNA stability." (PMID 39695216, 2024). "METTL3 promotes epithelial-mesenchymal transition in colorectal cancer by m6A modification of SNAIL mRNA, where SNAIL enhances the secretion of CXCL2 through the NF-κB pathway." (PMID 38605400, 2024). "In the field of colorectal cancer research, prior investigations have already elucidated the regulatory relationship between METTL3 and SNAIL." (PMID 38605400, 2024). "Our findings demonstrate that METTL3 promotes proliferation, invasion, migration, and inhibits apoptosis in colorectal cancer, highlighting its oncogenic potential." (PMID 38605400, 2024). "In colorectal cancer, METTL3 methylates SOX2 mRNA, allowing it to bind to the mRNA-binding protein IGF2BP2 at m6A sites, preventing SOX2 mRNA degradation and promoting protein expression." (PMID 38238831, 2024). "By marking m6A sites in flanking reverse complementary sequences, METTL3 induces circ1662 in colorectal cancer, which enhances colorectal cancer invasion and migration through YAP1 and SMAD3." (PMID 39550559, 2024). "Given the controversies surrounding the roles of m6A modification and METTL3 in different cancer types, our study underscores the potential involvement of METTL3 in colorectal cancer." (PMID 38605400, 2024). "On the contrary, targeted inhibition of METTL3/LDHA axis can improve the sensitivity of colorectal cancer cells to 5-FU in vivo and in vitro." (PMID 38709280, 2024). "lingling Wang demonstrated that depletion of the methyltransferases Mettl3 and Mettl14 enhanced response to anti-PD-1 treatment in colorectal cancer and melanoma." (PMID 38030537, 2024). "The Yap get into the nucleus and affected the transcription promotion of FOXD3 on METTL3, resulting in a systematic decrease in the level of m6A modification of overall mRNA in colorectal cancer cells." (PMID 37179374, 2023). "Further, M2-TAMs can promote lung adenocarcinoma immuno-resistance by enhancing METTL3-mediated m6A methylation, as well as inducing oxaliplatin resistance by increasing METTL3 in colorectal cancer cells." (PMID 37671161, 2023). "Collectively, our study revealed the unappreciated dual role of METTL3 as an m6A writer and a transcription regulator, which worked together in the same signaling pathway to drive colorectal cancer malignancy." (PMID 38001065, 2023). "The latest study related to colorectal cancer published in 2023 showed that METTL3 influenced the proliferation, migration, and invasion of colorectal cancer cells through regulating Notch1 and Hsa_circ_0000390." (PMID 36970605, 2023). "Further studies revealed that RUNX3 interacts with the METTL3 promoter and activates circMETTL3 transcription in colorectal cancer." (PMID 37996892, 2023). "In colorectal cancer, higher METTL3 expression in metastatic tissues was responsible for elevated SOX2 expression, which contributed to colorectal cancer cell stemness and malignancy." (PMID 38001065, 2023).